NDRG1 (N-myc downstream regulated 1)
Diseases named in the same sentence as NDRG1 in open-access papers (continued):
Sharing a sentence is not in itself a finding about the gene and the disease.
tumor (continued). "The loss of NDRG1 expression may accelerate tumor progression by promoting angiogenesis." (PMID 41409301, 2025). "Finally, we propose a therapeutic alternative for TNBC patients, whose overexpression of NDRG1 is associated with poorer survival and TGFβ1 status, by the combination of TGFβ and GSK3β inhibitors to potentially preventing tumor progression, recurrence, and chemoresistance." (PMID 36594086, 2023). "NDRG1 expression is induced in response to metabolic limitations imposed by oxygen and iron deprivation, suggesting that it may play an important role in the altered metabolism associated with poorly perfused tumor microenvironments." (PMID 29898756, 2018). "Such cleavage of NDRG1 in cancer cells may result in loss of NDRG1 tumour suppressive activity." (PMID 23634903, 2013). "RNA‐seq analysis revealed 1073 upregulated genes in macrophages co‐cultured with NDRG1 knockdown tumor cells compared to the lactate‐treated group." (PMID 40539245, 2025). "For instance, the amplification of the chromosomal fragment 8q24.2 is associated with amplifications of MYC and NDRG1 located on this fragment and is significantly correlated with homologous recombination deficiency (HRD) across tumour types." (PMID 40332138, 2025). "The Tumor-4 subcluster had proliferating features and was marked by Mki67 and additional cell cycle genes, such as Kif23 and Ndrg1." (PMID 41332581, 2025). "First, we found that NDRG1 knockdown in A549 cells significantly reduced lactate levels in the tumor–conditioned media (TCM)." (PMID 40539245, 2025). "This indicates that tumor cell‐derived NDRG1 regulates H3K18la levels in macrophages via lactate, thereby affecting macrophage function through epigenetic mechanisms." (PMID 40539245, 2025). "First, we knocked down NDRG1 in tumor cells, collected their TCM, and co‐cultured it with THP‐1‐derived macrophages or bone marrow‐derived macrophages (BMDMs)." (PMID 40539245, 2025). "Tumors in the LLC‐shNDRG1+M2 macrophage group were significantly smaller than those in the LLC‐shCtrl+M2 macrophage group, indicating that NDRG1 knockdown effectively suppresses tumor growth." (PMID 40539245, 2025). "It is worth noting that NDRG1 is a stress-responsive protein involved in hormone responses, cell growth, and differentiation, and acts as a tumor suppressor in many cell types." (PMID 40004070, 2025). "In this cell model, NDRG1 acts as a tumour suppressor by preventing nasopharyngeal tumorigenesis and metastasis by inhibiting Smad2-mediated EMT of nasopharyngeal cells." (PMID 40332138, 2025). "Preclinical studies demonstrated targeting NDRG1 suppresses tumor growth, alleviates immune suppression, and boosts anti‐PD‐L1 efficacy." (PMID 40539245, 2025). "Volcano plot analysis of differentially expressed genes showed that NDRG1 is markedly upregulated in tumor tissues, alongside several key metabolic genes, including LDHA, SLC16A1, PKM, HK1, and LDHB." (PMID 40539245, 2025). "We demonstrated that upregulation of NDRG1 enhances glycolysis and lactate production in tumor cells, driving the polarization of M2 macrophages and suppressing the activity of CD8+ T cells." (PMID 40539245, 2025). "Further analysis revealed significant H3K18la signals at the promoters of CD163 and other immunosuppressive genes, suggesting that tumor‐derived NDRG1 regulates the expression of these genes through lactate‐dependent H3K18la modifications." (PMID 40539245, 2025). "Specifically, in cancer cells positive for the phospho-NDRG1, the signal intensity peaked at the tumor-stroma interface and started to rapidly decline in the cells located farther from the stromal border." (PMID 40654607, 2025).
tumor (continued). "qRT‐PCR revealed a marked upregulation of NDRG1 mRNA in tumor tissues compared to adjacent non‐tumor tissues." (PMID 40539245, 2025). "This broader perspective on NDRG1 function is consistent with its paradoxical roles in cancer, where it has been reported to act as both a tumor suppressor and oncogene depending on the cellular context." (PMID 40462946, 2025). "qPCR analysis showed that macrophages co‐cultured with NDRG1 knockdown tumor cells exhibited significantly decreased expression of these immunosuppressive genes, while lactate treatment partially restored their expression." (PMID 40539245, 2025). "To investigate the expression pattern of NDRG1, we analyzed tumor and adjacent non‐tumor tissues from 20 matched LUAD patients, collected at Zhongshan Hospital." (PMID 40539245, 2025). "Western blot results showed that NDRG1 knockdown in tumor cells significantly reduced H3K18la levels in macrophages, whereas treatment with exogenous lactate partially restored H3K18la enrichment." (PMID 40539245, 2025). "In this study, we observed that NDRG1 exhibits an independent association with a more favorable prognosis in SKCM, suggesting its potential role as a tumor suppressor gene." (PMID 41409301, 2025). "The result of model with 10 genes showed that 6 genes of MYCN, NDRG1, TXNRD1, SNAPC2, PHOSPHO2 and CDCA8 were more significantly associated with diagnosis of tumor according to the statistical filter of P < 0.05." (PMID 40465781, 2025). "The study showed that NDRG1 knockdown, in combination with immune checkpoint inhibitors such as PD‐1/PD‐L1 antibodies, significantly suppressed tumor growth and improved survival rates." (PMID 40539245, 2025). "Next, we investigated the effects of tumor cell‐derived NDRG1 and lactate on gene expression in macrophages through RNA‐seq." (PMID 40539245, 2025). "Our findings demonstrate that NDRG1 contributes to enhanced glycolytic activity in tumor cells, leading to increased lactate production." (PMID 40539245, 2025). "In fact, Yang H et colleagues showed a significant correlation between VM expression and NDRG1 gene expression and tumour grade, and a probable regulation of tumour MVD by NDRG1." (PMID 40332138, 2025). "Subsequently, Western blot analysis corroborated these findings, confirming a significant increase in NDRG1 protein levels in tumor samples." (PMID 40539245, 2025). "The coordinated regulation of these genes further enhances the immunosuppressive effects of macrophages within the TME, highlighting the critical role of NDRG1 and lactate in tumor immune evasion." (PMID 40539245, 2025). "Given our findings that NDRG1 promotes an immunosuppressive tumor microenvironment through lactate‐mediated immune cell regulation, we next explored the therapeutic potential of combining NDRG1 targeting with αPD‐L1 therapy in a LUAD model." (PMID 40539245, 2025). "Conversely, the knockdown of NDRG1 expression in these tumor cells largely prevented the ability of Dp44mT to prevent metastasis." (PMID 40378957, 2025). "The role of CDX2 and NDRG1 as putative regulators for BLM tumor cell differentiation was verified using organoids derived from BLM tumors." (PMID 38893159, 2024). "Out of the differentially expressed proteins, NDRG1 emerged as one of the most significantly modulated between healthy and tumor samples." (PMID 39736699, 2024). "Since NDRG1 can also decrease nuclear β-catenin levels in PC cells, the mechanism of its activity in these tumor cells was important to examine." (PMID 38815861, 2024). "In agreement, data from spatial proteomics demonstrated a higher expression of NDRG1 in the tumor core and peripheral tumor." (PMID 39736699, 2024). "Our RNA velocity analysis suggested Ndrg1 as a potential additional driver for BLM tumor differentiation." (PMID 38893159, 2024). "Considering that HER2+ and TNBC tumours showed a greater enrichment overall for NDRG1, we studied BT474 and MDAMB231 cell lines in a hypoxic environment." (PMID 40530439, 2024).
tumor (continued). "Nuclear expression of NDRG1 was significantly enriched for Grade 3 tumours in the BC patient cohort, as well as specifically in the HER2+ and TNBC cases." (PMID 40530439, 2024). "NDRG1 has been shown to suppress tumor growth, migration, and invasion by suppressing several known pathways, including NF-κB, E-cadherin, EGFR, and WNT/β-catenin." (PMID 38611020, 2024). "NDRG1 can promote tumor growth through up-regulation of several proteins involved in angiogenesis (e.g., vascular endothelial growth factor and Interleukin-1α)." (PMID 38561462, 2024). "Different protein immunohistochemistry double immunostaining scores show that the expression levels of NDRG1 and Vimentin are correlated with tumor grade in HGG patients." (PMID 39668822, 2024). "NDRG1 has been shown to exhibit variability in its function depending on the tumour type or cell type it is expressed in." (PMID 40530439, 2024). "We examined a cohort of matched primary BC BrM tumours as well as a cohort of unselected BC and found NDRG1 expression in the majority of tumours in both the cohorts, further supporting NDRG1's role as an oncoprotein." (PMID 40530439, 2024). "The anti-oncogenic and anti-metastatic activities of NDRG1 are mediated by its ability to inhibit a broad range of oncogenic pathways responsible for angiogenesis, tumor growth, and metastasis." (PMID 38815861, 2024). "This contradictory role of NDRG1 on tumor angiogenesis and VM formation in different cancer types confirming its tissue-specific pleiotropic role in cancer." (PMID 38561462, 2024). "NDRG1 belongs to the group of proteins that respond to stress (Supplementary MS/MS Data 1), and was found to be strikingly upregulated in tumor samples compared to normal counterparts." (PMID 39736699, 2024). "Many studies have shown that DUSP5 and NDRG1 are tumor suppressors that can effectively inhibit the proliferation and metastasis of tumor cells." (PMID 39883515, 2024). "This is the first evidence of the interaction of NDRG1 with the tumor environment, highlighting a new role of this protein in cancer onset and progression." (PMID 39736699, 2024). "Using RNA velocity, we identified additional potential regulators of BLM tumor differentiation such as NDRG1." (PMID 38893159, 2024). "Within the matched BC‐BrM patient cohort, NDRG1 positivity was higher at the BrM stage of tumour progression." (PMID 40530439, 2024). "Although NDRG1 is mainly recognized as a tumor suppressor, recent studies have also shown it to be a metastatic promoter in a variety of malignancies." (PMID 38983911, 2024). "Consistent with previous studies, the current results demonstrated that over-expression of NDRG1 was correlated with higher tumor grade, stage, and lymphovascular invasion." (PMID 38561462, 2024). "Multiple studies indicate that iron chelators enhance their anti-cancer properties by inducing NDRG1, a known tumor and metastasis suppressor." (PMID 38983911, 2024). "Grade 3 tumours were significantly enriched for nuclear NDRG1 expression, whereas only 5% of Grade 1 and 2 tumours showed the expression of nuclear NDRG1." (PMID 40530439, 2024). "In our study, the tumor-suppressive function of NDRG1 in CRC was confirmed for silencing NDRG1 expression, leading to enhanced anoikis." (PMID 38891773, 2024). "To identify other potential driver genes for BLM tumor differentiation, we computed transcriptional dynamics using RNA velocity, which identified Ndrg1 as a potential regulator of BLM tumor epithelial cell differentiation." (PMID 38893159, 2024). "The upregulation of PKCα by the metastasis suppressor, NDRG1, is also of interest since PKCα acts as a tumor suppressor in other cancers because it promotes phosphatase 2A (PP2A)-family-dependent AKT inactivation." (PMID 38815861, 2024). "The NDRG1 gene has a significant tumor suppressive effect in tumors such as gastric cancer, colorectal cancer, ovarian cancer, prostate cancer, and renal cancer." (PMID 39668822, 2024).
tumor (continued). "It was found that NDRG1 can promote tumor angiogenesis and growth in certain cancers as lung carcinomas while suppressing angiogenesis and VM in others." (PMID 38561462, 2024). "Within the hormone receptor subtypes, TNBC and HER2+ groups had higher proportions of NDRG1 high cases, whereas ER+ tumours showed an equal distribution of high and low NDRG1 expressions." (PMID 40530439, 2024). "In this experiment, the NDRG1 gene was expressed in all specimens, with its immunoreactivity mainly located in the cytoplasm of tumor cells." (PMID 39668822, 2024). "While many studies have reported that these family members have tumor suppressive roles, recent studies have demonstrated that NDRGs, particularly NDRG1 and NDRG2, function as oncogenes, promoting tumor growth and metastasis." (PMID 38611020, 2024). "NDRG1 is overexpressed under stress conditions and proteomic data demonstrate an enrichment of stress-related biological processes in tumor tissues compared to healthy counterparts." (PMID 39736699, 2024). "The NDRG1+ macrophage cluster was located in the tumor center, indicating the tendency of those cells to chemotaxis, which supported the authors’ previous findings." (PMID 39272958, 2024). "Our previous studies designed and synthesized novel thiosemicarbazone anti-cancer drugs that induce NDRG1 expression and potently inhibit primary tumor growth in vivo in a variety of cancers including several PC models." (PMID 38815861, 2024). "The expression of VM in samples is closely related to the expression level of NDRG1 (P=3.98E-04) and tumor CNSWHO grade (P=0.019)." (PMID 39668822, 2024). "By analyzing the specimen data using relevant statistical methods, we found a significant correlation between the expression of VM and the expression level of the NDRG1 gene (P=3.98E-04), as well as the tumor CNS WHO grade (P=0.019)." (PMID 39668822, 2024). "Overall, the role of NDRG1 in either promoting or suppressing tumor progression is highly dependent on the specific type of tumor cell and its degree of differentiation." (PMID 39199357, 2024). "This suggests that tumor cells with higher NDRG1 expression tend to grow slower and are less likely to spread." (PMID 37858101, 2023). "Our investigation by Spearman's rank test showed the strongest correlation coefficients between global NDRG1 staining and global p-NDRG1, p-NDRG1(C), and p-NDRG1(N) staining in tumor tissue specimens collected after surgery." (PMID 36594086, 2023). "Since tumor tissues are heterogeneous in terms of gene expression patterns, single cell gene expression profiling is needed to elaborate expression of NDRG1 in relation with pathological state." (PMID 37249826, 2023). "Consistently, the results of immunohistochemical analysis also showed that the expression of NDRG1 was significantly increased in tumor tissues compared with adjacent normal tissues." (PMID 37208604, 2023). "To validate these observations, we analyzed NDRG1 expression by immunohistochemistry in tumor tissue (n=75) collected from a total cohort of 83 TNBC patients after surgery." (PMID 36594086, 2023). "Immunofluorescence histochemistry results showed that PKCδ was overexpressed and NDRG1 was downregulated in CRC tumor tissues." (PMID 36816970, 2023). "NDRG1, commonly referred to as a metastasis suppressor protein, is expressed across various tumor types." (PMID 38235128, 2023). "By analyzing the expression characteristics of NDRG1 in the GSE14520 and HCC cohorts of the ICGC and TCGA databases, we found that NDRG1 exhibited higher expression levels in tumor tissues than in normal tissues (p < 0.05)." (PMID 37208604, 2023). "Inconsistent and variable results in TNBC cell lines have been reported when assessing the role of NDRG1 on proliferation, metastatic abilities, and tumor-initiating cells in TNBC cell lines 9,17,18." (PMID 36594086, 2023). "While having pleiotropic properties, in the context of PCa, NDRG1 functions as broadly tumor-suppressive." (PMID 37894914, 2023).